IRF7 (interferon regulatory factor 7)
Diseases named in the same sentence as IRF7 in open-access papers (continued):
Sharing a sentence is not in itself a finding about the gene and the disease.
sarcopenia (1 paper, 2025). Progressive decline in muscle mass due to aging which results in decreased functional capacity of muscles. "Functional studies using in vitro or in vivo models (e.g., gene knockdown or overexpression) to elucidate the mechanistic roles of key genes such as SERPING1 or IRF7 in HL and sarcopenia." (PMID 41137352, 2025). "IRF7, a master regulator of type I interferon responses, emerges as a pivotal shared gene in both ARHL and sarcopenia, implicating its role in immunometabolic crosstalk across these conditions." (PMID 41137352, 2025).
scleroderma (1 paper, 2022). Scleroderma is a rare autoimmune connective tissue disorder characterized by abnormal hardening of the skin and, sometimes, other organs. "The results of RNA-seq also showed that the expressions of cytokines IL-1β and OSM and the key transcription factor IRF7 in scleroderma were down-regulated in GSDMD KO mice." (PMID 35396386, 2022).
Splenomegaly (1 paper, 2018). Abnormal increased size of the spleen. "Among predicted target genes of these up-regulated miRNAs, genes related to IFN-α and β production as well as the innate immune response (e.g., Irf7, Dhx58, Oas1b, Mx2) were down-regulated in PPVL-induced splenomegaly." (PMID 30573742, 2018).
squamous cell carcinoma (1 paper, 2018). A carcinoma arising from squamous epithelial cells. "The tumor tissue had higher expressions of IRF7 and STAT2 than the normal tissue in the all subject group (p value 0.003 and 0.01, respectively) and in the subgroup of squamous cell carcinoma (SCC) (p value 0.03 and 0.02, respectively)." (PMID 30305853, 2018).
staphylococcus aureus infection (1 paper, 2022). An infectious process in which the bacteria Staphylococcus aureus is present. "Next two genes, Irf7 and Itgam are associated with NOD-like receptor signaling pathway and Staphylococcus aureus infection pathway, respectively." (PMID 36591261, 2022).
subarachnoid hemorrhage (1 paper, 2024). A serious neurological disorder characterized by intracranial hemorrhage into the subarachnoid space. "In addition, the Tlr2/Irf7 signaling axis has been associated with microglia-mediated inflammation after subarachnoid hemorrhage in mice." (PMID 38570482, 2024).
synucleinopathy (1 paper, 2025). A neurodegenerative disease that is characterized by the abnormal accumulation of aggregates of alpha-synuclein protein in neurons, nerve fibers or glial cells. "Our observations at gene level, such as upregulation of chemokine and interferon response genes CCL2, IRF7, IL7R, and the immunomodulatory checkpoint gene VSIR, further reflect the complex immune environment within synucleinopathy appendixes." (PMID 41279937, 2025).
vasculitis (1 paper, 2013). "Ifng also enhances expression of Irf1, Irf7, and Irf9, transcription factors that regulate the expression of immune-related genes that may also lead to severe inflammation of the arteries and subsequent lethal vasculitis." (PMID 24063402, 2013).
Wheezing (1 paper, 2021). A high-pitched whistling sound associated with labored breathing. "They found that some children, in response to an acute viral-induced wheezing illness, have different upper airway gene network expression patterns in their anti-viral Interferon Regulatory factor 7 (IRF7) network." (PMID 34912343, 2021).
infection (405 papers, 2007 to 2026). The state of being infected such as from the introduction of a foreign agent such as serum, vaccine, antigenic substance or organism. "Taken together, these results suggest that among various IRFs, only the differential expression of IRF7 and its associated type-I IFNs observed in LmCen–/– immunization compared to LmWT infection predominantly determine LmCen−/− induced protective immunity." (PMID 39702382, 2024). "In response to pathogenic infection, phosphorylation of IRF7 is triggered, leading to its translocation from the cytoplasm to the nucleus." (PMID 38482001, 2024). "We next evaluated the impact of IRF7 signaling deficiency on the development of Th1 immune response by comparing the cytokine production in WT and IRF7−/− mice following the challenge infection with virulent L. donovani parasites." (PMID 39702382, 2024). "This analysis also confirms our previous findings of an enrichment in rare pLOF variants of 13 genes involved in TLR3- and IRF7-dependent type I IFN immunity to seasonal influenza virus in critical cases relative to controls with mild/asymptomatic infection." (PMID 37020259, 2023). "IRF7 and its associated molecules lead to the activation of canonical pathways involved in the cellular-mediated response to infection." (PMID 36827648, 2023). "In contrast, in the CNS IRF7 deficiency leads to high expression levels of IFN-I upon infection, indicating differential regulation of IFN-I expression in the brain." (PMID 37737190, 2023). "Infection with A. actinomycetemcomitans caused a significant upregulation in the expression levels of Isg15, Mx1, Mx2, Irf3, Irf7, Tlr-2, Tnf-α, Cxcl-1, and Il-6 genes." (PMID 37929187, 2023). "After pathogenic infection, IRF7 changes from an inactive to activated state by phosphorylation, and the activation of IRF7 requires two phosphorylation events." (PMID 37638030, 2023). "Of note, the infection caused significant upregulation in mRNA expression level of interferon-stimulated genes (Isg15, Mx1, Mx2, Irf3, and Irf7) and pro-inflammatory cytokines (Tnf-α, Cxcl-1, and Il-6 genes)." (PMID 37929187, 2023). "Excessive inflammation has been a risk factor for infection, highlighting an unmet need for IRF7 inhibition for reducing excessive inflammation." (PMID 36269754, 2022). "The RV144 vaccine regimen strongly induced the IFNγ pathway, more specifically the activation of IRF7, which was associated with reduced risk of acquisition of infection." (PMID 34806296, 2021). "In mice, knockdown of IRF3 is not detrimental to the IFN response to IAV, however knockdown of IRF7 leaves mice much more susceptible to infection and a double knockout of both transcription factors renders mice unable to produce IFN-α or IFN-β." (PMID 32477965, 2020). "We compared findings with Irf-7−/− mice, which showed high viral replication in the brain and weight loss but recovered from an infection." (PMID 32951602, 2020). "While IRF7-deficient mice have undetectable bioactivity of IFN-I during early infection, they are still capable of producing normal levels of IFN-β." (PMID 30791575, 2019). "The enhanced survival of the CD8+ T cells in OASL1-deficient mice is dependent on higher IFN-I production early following infection (days 2–3 post-infection), which is the consequence of loss of negative regulation of IRF7 by OASL1." (PMID 30791575, 2019). "Interferon regulatory factor 7 (IRF7) is a crucial regulator of type I IFN against pathogenic infection, which activates IRF7 by triggering signaling cascades from pathogen recognition receptors (PRRs) that recognize pathogenic nucleic acids." (PMID 31430947, 2019). "IRF7 is a crucial regulator of type I IFN against pathogenic infection and the TRIM family plays important roles in innate immunity; they are also inducible by LPS and poly(I:C) stimulation." (PMID 31430947, 2019). "Double IRF-3/IRF-7 deficient mice infected with PbA were resistant to ECM upon infection confirming a role for IFN-I in ECM." (PMID 25157202, 2014).
infection (continued). "IRF7 is the master regulator of type I IFNs against pathogenic infections, which activate IRF7 by triggering signaling cascades from PRRs that recognize pathogenic nucleic acids." (PMID 22783275, 2012). "Our findings were consistent with the results of these animal experiments, suggesting that IRF7 might also be one of the targets implicated in severe E11 infection leading to liver injury." (PMID 39045132, 2024). "The child’s parents were heterozygous for two different loss-of-function mutations in the IRF7 transcription factor, thus they were able to produce enough IRF7 to prevent severe infection; however, the child inherited both mutations which led to a complete loss of functional IRF7." (PMID 38275224, 2024). "IRF7, also known as Interferon Regulatory Factor 7, is a well characterized transcription factor that is known to regulate type I interferons (IFNs) against pathogenic infections from parasites, fungi, bacteria, and viruses." (PMID 36827648, 2023). "Interestingly, IRF7 deficient mice were unable to control lymphocytic choriomeningitis virus (LCMV) replication due to reduced IFN-I production in the early stages of infection." (PMID 37251373, 2023). "IRF7 is a key regulator of type-I IFN in combating pathogenic infections." (PMID 38140617, 2023). "To summarize, the abnormal expression of CXCL10, ICAM1, CD40, IRF7, and B2M may be the main cause of tracheal dysfunction after infection with coronavirus." (PMID 34504502, 2021). "Humans who have mutations in IRF7 are more susceptible to life threatening infections by IAV." (PMID 32477965, 2020). "In IRF7-/- mice, the peak of infection (7 dpi) was associated with increased nuclear-to-cytoplasmic HMGB1 translocation in the epithelium, increased IL-33 levels in the airway lumen, and the infiltration of neutrophils, which can process IL-33 to a more biologically active form." (PMID 32658914, 2020). "Additionally, IRF7−/− mice infected with SINV died 5–8 days after infection due to immune-mediated neurotoxicity associated with failure to regulate the production of inflammatory cytokines." (PMID 30909385, 2019). "Inactive IRF7 resides in the cytoplasm as a latent form when pathogenic infection triggers IRF7 phosphorylation and translocation into the nucleus, where with other co-activators it forms a transcriptional complex that binds to the promoter regions of target genes to activate transcription." (PMID 22783275, 2012). "UBE3C was shown to regulate WT and phosphorylation deficient IRF3 and IRF7 levels in homeostatic conditions, as well as during infection, suggesting that it might target the IRFs during steady state conditions as a part of protein QC, and independently of their activation." (PMID 33808506, 2021). "However, in the presence of the strong Irf-7-mediated response associated with infection of 14M1.4 cells, we observed a reciprocal regulation of genes related to MHCI- and MHCII-restricted antigen presentation, with elevated levels of transcripts for MHCI, TAP1 and tapasin." (PMID 20300600, 2010). "We also show for the first time that IFNβ and IRF7 make strong contributions to the harmful action of IFN-I in L. monocytogenes infection because the lower levels of IFN-I production in these mouse lines were correlated with decreased susceptibility to lethal infection." (PMID 19325882, 2009). "We show that PHEV activates RIG-I-MAVS signaling but hijacks this pathway to induce a delayed IRF7-dependent interferon (IFN-I) response (>12 h post-infection), permitting unchecked replication prior to late-phase immunity." (PMID 41910148, 2026). "Our findings revealed that all three RNA viruses significantly upregulated the expression of bat IRF7 after 3 h of infection." (PMID 40108733, 2025). "Three RNA viruses, Newcastle disease virus (NDV), avian influenza virus (AIV), and vesicular stomatitis virus (VSV), significantly upregulated bat IRF7 mRNA expression after infection of TB 1 Lu cells." (PMID 40108733, 2025).
infection (continued). "Of the gene markers analyzed, male TLR7ko mice only showed significant increases in IL5 and IRF7 expression following infection." (PMID 40143355, 2025). "We also found upregulation of TLR2/4 and IRF7 relative to uninfected cells, and these were also enhanced during Mcat mono-infection and coinfection." (PMID 40492732, 2025). "In the visceral in vivo model using L. donovani, protection against the infection was conferred in a IRF7-dependent manner." (PMID 40794782, 2025). "The capacity of JEVNSW/22 to cause lethal neuroinvasive infection in mice was significantly diminished compared to JEVNakayama and JEVFU, with only one Irf7−/− mouse succumbing to JEVNSW/22 infection out of 63 infected C57BL/6J or Irf7−/− mice." (PMID 40295675, 2024). "Several lines of evidence in our study indicate that the reduction of IFN-α/β levels in LmCen–/– infection is mediated by the spontaneous reduction of IRF7 expression." (PMID 39702382, 2024). "In contrast, IRF7–/– mice produced only background level of type-I IFNs after infection with LmWT or LmCen–/– parasites on days 0, 2 and 7 p.i.." (PMID 39702382, 2024). "The importance of IRF7 in infection‐related immune response and tissue injury has recently garnered more attention." (PMID 39166412, 2024). "Transcripts associated with type-I IFN pathway showed that enrichment of IRF7 occurred in both LmWT and LmCen–/– infections." (PMID 39702382, 2024). "This confirmed that C57BL/6J and Irf7−/− mice that succumbed to infection had significantly increased leukocyte infiltrates." (PMID 40295675, 2024). "The mRNA expression levels of RIG-I, MDA5 and key adapter proteins, including MAVS, IRF7 and NF-κB, were significantly upregulated in the infection group at 24 hpi and 48 hpi." (PMID 39502173, 2024). "The use of Irf7−/− mice to increase lethal neuroinvasive infection compared to C57BL/6J was only suitable for JEVFU and JEVNSW/22." (PMID 40295675, 2024). "E. coli‐infection induced upregulation of IRF7 and phosphorylation of IRF7 via activating MyD88‐IRAK4‐IRAK1/TRAF6 axis." (PMID 39166412, 2024). "Some mice that lost >8% body weight and then recovered had persistent lesions detectable at the latest time point sampled (up to day 32 for C57BL/6J and day 21 for Irf7−/−), consistent with persistent neurological sequelae in humans that survive infection." (PMID 40295675, 2024). "IRF7 is a master transcription factor of Type I interferon-dependent immune responses, making it a potential target for infection control." (PMID 39421254, 2024). "Following immunization with LmCen−/−, levels of IFN-α/β and mRNA expression of IRF7 were measured and compared to those in LmWT infection." (PMID 39702382, 2024). "DF-1 cells were transfected with pcDNA3.1-His-IRF7 plasmid followed by infection with 1 MOI attenuated IBDV, B87." (PMID 39872942, 2024). "The western blot analysis results indicated that as the infection time extended, the expression of IRF7 protein gradually increased." (PMID 39872942, 2024). "It is worth noted that infections with different virulent strains of IBDV differing in their impact on IRF7 expression was observed in our study." (PMID 39872942, 2024). "JEVNSW/22, JEVNakayama, and JEVFU infection of Irf7−/− mice (dose 5 × 103 CCID50) resulted in robust viremias, while MVEVTC123130 viremia was significantly lower than JEV (p < 0.0001)." (PMID 40295675, 2024). "In line with previous reports suggesting mild interferon responses to SARS-CoV-2 infections, OAS1 and IRF7 were only slightly elevated in THP-1 cells after infection with SARS-CoV-2 under normoxia and hypoxia." (PMID 37377965, 2023). "The protein levels of NF-κB/RelA and IRF3 are stable within 24 h infection, while the level of IRF7 is increased at 12 h p.i." (PMID 37423306, 2023). "In vivo infection of WT and Irf7-/- mice and in vitro culture of BMDM, BMDC, MEF, and primary cortical neurons." (PMID 37251373, 2023).
infection (continued). "Another group compared the response of mice deficient in IRF3, IRF7, or both IRF3 and IRF7 following infection with CHIKV." (PMID 37766276, 2023). "Approximately 70% of the mice succumbed to LGTV infection, indicating that the high amount of IFN-I produced upon infection in Irf7−/− mice protects the mice from death although the massive IFN-I production was not able to protect neurons from infection." (PMID 37737190, 2023). "IRF7 expression was significantly up-regulated by the M51R mutant infection compared to the mock infection, whereas its expression between WT and the mock infection was comparable." (PMID 37513744, 2023). "We observed that expression of inflammatory chemokine CCL2 and cytokine TNF-α increased in the brain of Irf7−/− during the course of infection." (PMID 37737190, 2023). "229E viral protein synthesis was increased in cells treated with siRNA oligos against IRF3 or IRF7 compared to siRNA controls at 2 days after infection." (PMID 37197656, 2023). "The levels further increase in all brain parts of Irf7−/− animals 7 days post-infection compared to WT and Irf3−/− mice." (PMID 37737190, 2023). "In response to infection by SARS-CoV-2, Irf7 is among the genes most highly induced in infected mice, suggesting that the recognition of the infection by cellular sensors and downstream signaling molecules is functional." (PMID 36851549, 2023). "In 3D enteroids, the phagocyte chemoattractant genes, IL8 (CXCLi1) and IL8L (CXCLi2) and transcription factors, IRF1 and IRF7, were induced by STm infection." (PMID 37854334, 2023). "In the presence of VitD and rxrbb during GCRV infection, the double knockout of grass carp vdra and vdrb significantly induced the transcriptions of mda5, rig-I, mavs, tbk1, irf3, irf7, and mx1." (PMID 37466438, 2023). "IRF7 plays a crucial role as an important transcriptional regulator of cellular responses in a variety of inflammatory diseases, cancers and infections." (PMID 37251373, 2023). "A significantly elevated amount of viral RNA was found in serum of Irf7−/− mice 2 days post-infection when compared to WT and Irf3−/− mice." (PMID 37737190, 2023). "In vivo infection of WT and Irf7-/- mice and in vitro culture of BMDM, BMDC, and macrophage cell lines." (PMID 37251373, 2023). "Here, we summarize recent advances in the role of IRF7 as a multifunctional transcription factor in inflammation, cancer and infection by regulating IFN-I production or IFN-I-independent signaling pathways." (PMID 37251373, 2023). "The expression of IRF1 and IRF7 was increased at 3 and 4 days after infection compared to uninfected controls." (PMID 37197656, 2023). "First, the expressions of IRF1, IRF3 and IRF7 were confirmed and then the expression levels of the ISGs before infection were analyzed." (PMID 37197656, 2023). "The high basal level of IRF7 expressed in pDCs also helps pDCs to express type I IFN at levels 10–100 fold higher than other types of cells upon infection." (PMID 37766322, 2023). "While only low numbers of peripheral CD45+ immune cells were observable in WT mice upon LGTV infection, we found a substantial increase of infiltrating cells in the brains of Irf7−/− mice on day 7 post-infection." (PMID 37737190, 2023). "CVA6 infection leads to the increased expression of ISGs, including Oas2, Irf7, Ddx60, Ifit3, Ddx58, and Isg15, which exhibit immunopathogenic potential and are implicated in neural inflammation." (PMID 36851724, 2023). "Significantly, our results showed that the expression of six major adaptor molecules (Myd88, IRAK2, IRAK4, TRAF3, TBK-1 and IRF7) downstream of RNA sensors were dramatically decreased in the PAMs with a PRRSV-ADE infection." (PMID 36680075, 2022). "The present study suggests that duRIG-I-mediated IRF-7 signaling was down-regulated by duLGP2 during DTMUV infection, leading to the down-regulation of IFN-β promoter activity." (PMID 35784309, 2022).